ADD1 (adducin 1)
Description:
Membrane-cytoskeleton-associated protein that promotes the assembly of the spectrin-actin network. Binds to calmodulin.
Synonyms: ADDA
Tractability: Antibody: its Gene Ontology location is reachable by antibodies, with high confidence; UniProt places it where antibodies can reach, with medium confidence; the Human Protein Atlas places it where antibodies can reach. PROTAC: ubiquitination databases record sites on it; its protein half-life has been measured.
Gene: Protein-coding gene on chromosome 4 (2,843,576 to 2,930,082, forward strand). Ensembl gene ENSG00000087274.
Subcellular location: Cytoplasm, cytoskeleton; Cell membrane
Subcellular location (Human Protein Atlas): Plasma membrane; Nucleoplasm
Pathways (Reactome):
Cellular responses to stimuli: XBP1(S) activates chaperone genes
Programmed Cell Death: Caspase-mediated cleavage of cytoskeletal proteins
Transport of small molecules: Miscellaneous transport and binding events
Gene Ontology:
Molecular function: actin filament binding; cadherin binding; cytoskeletal anchor activity; protein binding; protein dimerization activity; protein heterodimerization activity; protein homodimerization activity; RNA binding; RNA polymerase II-specific DNA-binding transcription factor binding; spectrin binding; actin binding
Biological process: actin cytoskeleton organization; actin filament bundle assembly; barbed-end actin filament capping; cellular response to calcium ion; positive regulation of adherens junction organization; positive regulation of establishment of endothelial barrier; regulation of actin filament polymerization; cytoskeleton organization; positive regulation of cellular component organization; positive regulation of developmental process; regulation of cellular component size; regulation of multicellular organismal development
Cellular component: adherens junction; cytoplasm; F-actin capping protein complex; focal adhesion; nucleoplasm; nucleus; plasma membrane; cytoskeleton; cytosol; postsynaptic density; spectrin-associated cytoskeleton; cell junction
Genetic constraint (gnomAD): Loss-of-function variants: 23 observed, 84.16 expected, observed/expected ratio (o/e) 0.27, 90% interval 0.2 to 0.39. The upper end of that interval is the gene's LOEUF score, 0.39, which puts it in group 1 of 6, group 1 being the genes least tolerant of losing a copy. Missense variants: 948 observed, 1,068.8 expected, observed/expected ratio (o/e) 0.89, 90% interval 0.84 to 0.94. Synonymous variants: 373 observed, 412.49 expected, observed/expected ratio (o/e) 0.9, 90% interval 0.83 to 0.99.
Homologues: Orthologues: chimpanzee ADD1 (96% identical), dog ADD1 (93% identical), rat Add1 (92% identical), macaque ADD1 (92% identical), pig ADD1 (89% identical), mouse Add1 (85% identical), guinea pig ADD1 (84% identical), tropical clawed frog add1 (77% identical), zebrafish add1 (73% identical), rabbit ADD1 (72% identical), Drosophila melanogaster hts (35% identical), Caenorhabditis elegans add-2 (22% identical). Paralogues in human: ADD3 (46% identical), ADD2 (43% identical).
Diseases named in the same sentence as ADD1 in open-access papers:
ADD1 is named in the same sentence as 52 diseases in open-access papers, as found by Europe PMC text mining. Sharing a sentence is not in itself a finding about the gene and the disease. The quoted sentences say what the papers report.
Hypertension (36 papers, 2007 to 2025). The presence of chronic increased pressure in the systemic arterial system. "Previous studies have found potential interactions between ACE, AGT, angiotensin II type 1 receptor (AGTR1), and α adducin (ADD1) variants and correlations between them and clinical endpoints in individuals with hypertension." (PMID 37091860, 2023). "ADD1: Variants in the Adducin 1 (ADD1) gene, which plays a role in renal sodium reabsorption, have been linked to an elevated risk of hypertension." (PMID 37965396, 2023). "Recently, a study has shown that a genetic polymorphism (rs4961, Gly460Trp) in ADD1 associated with hypertension is a genetic biomarker of hypertension in Asians." (PMID 35999587, 2022). "Among three subunits composing adducin (ADD), a mutation of the α-subunit encoded by ADD1 can lead to an increase in renal sodium reabsorption, subsequently causing hypertension." (PMID 35740428, 2022). "In our study, since the 4 individuals with MetS had the same c.16C > T p.(Arg6Cys) variant in hypertension-related ADD1, this was considered the most frequent variant." (PMID 35999587, 2022). "For example, low methylation of the α-adducin (ADD1) gene promoter increases the risk of essential hypertension, and the variation of ADD1 is associated with the risk of colorectal cancer." (PMID 35513851, 2022). "Lower ADD1 promoter DNA methylation has been found to be related to higher risk of essential hypertension." (PMID 35740428, 2022). "It was found for the Chinese population that ADD1 CpG methylation level was associated with essential hypertension (EH) with a significantly higher methylation degree in females than in males." (PMID 34055401, 2021). "A cross-sectional study of a Chinese population showed a significant interaction between the CYP11B2 genotype and DNA methylation (CpG1 methylation) of the ADD1 gene promoter and alcohol consumption on the risk of hypertension." (PMID 30857519, 2019). "In a general Japanese population, a high sodium intake strengthened the association of AGT T174 M and ADD1 G460 W (only women) polymorphisms with hypertension and SBP levels, respectively." (PMID 30857519, 2019). "In essential hypertension, a case-control study found that the extent of ADD1 promoter methylation was inversely associated with the risk of hypertension in a gender-dependent manner." (PMID 29862265, 2018). "In vitro and in vivo studies based on ADD1 mutation have unraveled the primary molecular mechanism that underlies the transition from normotension to hypertension in the context of sodium handling." (PMID 29862265, 2018). "Among these polymorphisms, the ADD1-Gly460Trp gene variant was identified as a candidate gene for hypertension." (PMID 29862265, 2018). "In a study of the DNA methylation levels of 5 CpG dinucleotides in 62 patients, reduced promoter methylation of the α-adducin (ADD1) gene was been shown to be linked to an increased essential hypertension risk." (PMID 29649151, 2018). "Although α-adducin is a cytoskeletal protein, an ADD1 variant has been implicated in stimulation of renal sodium reabsorption and, subsequently, hypertension." (PMID 29649151, 2018). "We observed no significant gene-environment interaction between the candidate SNP, ADD1_rs4961, and hypertension in relation to RCC risk." (PMID 27686058, 2016). "According to Li and colleagues, two regulatory genes, the C allele at rs2070744 of the NOS3 and the T allele of rs4961 of the ADD1 gene, are significantly associated with the high prevalence of hypertension among Tibetan patients." (PMID 25953970, 2015). "Many previous studies have reported associations of ADD1 variants with hypertension, renal functions and renal diseases, in different populations including Chinese." (PMID 24658007, 2014). "ADD1 encodes the alpha subunit of the cytoskeleton protein adducin, which plays an important role in hypertension and renal function via sodium homeostasis." (PMID 24658007, 2014).
Hypertension (continued). "Polymorphisms in the human ADD1 gene have also been associated with hypertension and responsiveness to antihypertensive medications in several populations." (PMID 23890820, 2013). "The association between polymorphisms of α-adducin (ADD1) gene and essential hypertension is still unclear." (PMID 23509723, 2013). "The authors reported that chromosome rs4963 within the ADD1 gene is associated with the development of essential hypertension in Chinese people, particularly males." (PMID 24224165, 2013). "Not surprisingly, a number of studies have investigated the association of α-adducin gene (ADD1) polymorphisms with essential hypertension in the past two decades." (PMID 23509723, 2013). "The goal of our study is to investigate the contribution of promoter DNA methylation of α-adducin (ADD1) gene to the risk of essential hypertension (EH)." (PMID 23691048, 2013). "In an article featured in this special issue, L. Zhang and coworkers investigated the association between polymorphisms of α-adducin (ADD1) gene and essential hypertension." (PMID 24224165, 2013). "Several studies have described the role of ADD1 gene polymorphism in hypertension worldwide and there is paucity of data relevant to the Indian population." (PMID 20838486, 2010). "Genetic variant of alpha adducin (ADD1) gene have been implicated as a risk factor for hypertension." (PMID 20838486, 2010). "Given its clinical significance, we investigated the association between ADD1 Gly460Trp gene polymorphism and essential hypertension in an Indian population." (PMID 20838486, 2010). "Some studies have found an association with C1797T polymorphism (rs4984) with hypertension (particularly in the presence of ADD1 460Trp allele) and systolic BP, depending upon the gender and genetic background of the subjects being studied." (PMID 17854487, 2007). "Similarly, Kundu and Anand investigated ADD1 polymorphisms in the context of hypertension, identifying seven damaging nsSNPs, including the well-characterized G460W (rs4961), which is thought to disrupt renal ion transport and blood pressure regulation." (PMID 40869965, 2025). "Therefore, the functional ADD1 polymorphism is considered a potential genetic marker for hypertension." (PMID 41020232, 2025). "Similarly, Kundu and Anand evaluated nine nsSNPs in ADD1 and identified G460W (rs4961) as structurally destabilizing and associated with hypertension." (PMID 40869965, 2025). "Mutations in ADD1 have been shown to be associated with both human and rat hypertension." (PMID 31275642, 2019). "In human case-control association studies, ADD1 gene with the mutant allele (460Trp) showed an increased risk of hypertension and a reduced sodium content in red blood cells with a faster rate of ion transport than those with the wild-type ADD1 460GlyGly homozygote allele." (PMID 29862265, 2018). "Additionally, ADD1 Ser617Cys polymorphism (rs4963) was reported to be associated with hypertension in the Asian population." (PMID 29862265, 2018). "ADD1 methylation has been previously shown to represent a risk factor for EH in males (CpG2-5) and females (CpG1), wherein lower ADD1 methylation causes higher protein expression and increased Na+–K+ pump activity, resulting in Na+ reabsorption and hypertension." (PMID 29752343, 2018). "Importantly, the NSC cluster contains the Add1 gene encoding Alpha-adducin, in which the amino acid substitution F316Y has been identified as a cause of hypertension in MHS." (PMID 23890820, 2013). "Moreover, gender dimorphism of the association between hypertension and ADD1 Gly460Trp was observed in Caucasians." (PMID 23691048, 2013). "However, epidemiological studies have shown that the contribution of ADD1 Gly460Trp mutation (rs4961) to hypertension varies among different ethnic groups." (PMID 23691048, 2013).
Hypertension (continued). "We defined coevolutionary clusters that were unique to each disease strain and among these clusters of genes identified two genes, Add1 and Gimap5, previously shown by positional cloning to underlie susceptibility to hypertension in MHS and lymphopenia and diabetes in BBDP, respectively." (PMID 23890820, 2013). "The present study indicated that rs4963 within ADD1 gene was associated with essential hypertension in Chinese population, which might be related to altered exonic splicing and disrupted gene regulation." (PMID 23509723, 2013). "In conclusion, the present study indicated that rs4963 within ADD1 gene was associated with essential hypertension in Chinese population, which might be related to altered exonic splicing and disrupted gene regulation." (PMID 23509723, 2013). "In addition, sodium-rich diet, high alcohol intake, genetic modification of the NOS3 (Nitric Oxide Synthase 3) gene and ADD1 (Adducin 1), could explain the high prevalence of hypertension in this same population as they are risk factors." (PMID 37824544, 2023). "Therefore, we carried out a case-control study and an interaction analysis to verify whether ADD1 gene is associated with hypertension in the Chinese population." (PMID 23509723, 2013). "Series of studies in humans reveal that mutation of ADD1 gene may lead to the stimulation of the sodium and potassium-adenosine triphosphatase (ATPase) activity in renal tubular cells, increased renal sodium reabsorption, and subsequently hypertension." (PMID 23509723, 2013). "In this study, we hypothesized that the aberrant ADD1 methylation may cause hypertension." (PMID 23691048, 2013). "We speculated that lower ADD1 methylation led to higher expression of α-adducin which resulted in an increased activity and expression of Na+-K+-pump and eventually caused high Na+-reabsorption and hypertension." (PMID 23691048, 2013). "Therefore, it is necessary to explore whether there are any other SNPs within ADD1 gene that are also associated with essential hypertension." (PMID 23509723, 2013). "Dysfunction of ADD1 can lead to hypertension by enhancing sodium reabsorption in renal tubular epithelial cells, while pharmacological inhibition of ADD1 can significantly lower blood pressure." (PMID 41020232, 2025). "Mutations in the genes ADD1, ADD2, and ADD3 have been linked to hypertension, neurodevelopmental disorders, and cancer." (PMID 40869965, 2025). "A previous study has shown that ADD1 is a salt-sensitive gene that plays a role in the etiology of hypertension." (PMID 35999587, 2022). "ADD1, ADM, and ADRB2 were included for the NGS analysis for detecting variants related to hypertension." (PMID 35999587, 2022). "Aldosterone synthase (CYP11B2) and α-adducing (ADD1) are candidate genes that play key roles during essential hypertension (EH) incidence." (PMID 36035164, 2022). "This animal model harbors a genetic variation within the cytoskeletal protein α-adducin (Add1 Phe316Tyr), and all the rats that carry this variation will develop hypertension with age." (PMID 24752134, 2014). "A final candidate gene from this region, ADD1, is localized to the erythrocyte membrane and is involved in renal sodium handling and hypertension." (PMID 22577559, 2012). "We also investigated adducin, the heterodimeric cytoskeleton protein whose three subunits are encoded by ADD1, ADD2 (protein accession number C9J080, FC = 0.00), and ADD3, respectively; the role of adducin in hypertension and its downregulation-related disorders have been reported." (PMID 36002804, 2022). "ADD1 also directly participates in the pathophysiology of hypertension." (PMID 35740428, 2022). "In conclusion, neither the present study nor the meta-analysis offers evidence for the ADD1 variant 460Trp in the causation of essential hypertension suggesting that it is unlikely to be a predisposing factor in hypertension." (PMID 20838486, 2010).
Hypertension (continued). "Interestingly, four of these genes (KCNMB1, NEDD4L, ADD1 and NPR3) have been implied in genetic susceptibility for hypertension, while two genes have been associated with genetic susceptibility for stroke (PDE4D) or myocardial infarction (ADD1)." (PMID 19750006, 2009). "Thus, we carried out a case-control study and an interaction analysis to test whether ADD1 is a common candidate gene for hypertension in the Chinese population." (PMID 23509723, 2013). "However, most studies focus on ADD1 G460W polymorphism, and whether other single nucleotide polymorphisms (SNPs) in ADD1 gene were associated with essential hypertension is not clear." (PMID 23509723, 2013). "Most of these analyses failed to provide evidence for the genetic association of ADD1 G460W polymorphism with essential hypertension in global population; but it is suggested that the W carrier might increase the risk of essential hypertension in Han Chinese population." (PMID 23509723, 2013). "Some hypertension-related genes exhibited high deletion frequency, including NPPA, ADD1, and INSR." (PMID 35513851, 2022). "The ADD1 Gly460Trp-polymorphic locus is an important predictor of arterial hypertension development in the Ukrainian population, but other nongenetic factors should be considered in further studies." (PMID 34055401, 2021). "In addition, the hypomethylation of TLR2, IFN-γ gene, ADD1, AGTR1, and GCK correlated with hypertension, the CES = 2.3%, 95% CI, −2.51–7.07." (PMID 31805646, 2019).
lung carcinoma (5 papers, 2007 to 2025). "ADD1 has also been found to be upregulated in asbestos-exposed lung cancer patients." (PMID 17331233, 2007). "AKT signaling has been shown to promote ZNF322A protein stability and transcriptional activity, which in turn positively regulates transcription of alpha-adducin (ADD1) and cyclin D1 (CCND1) to promote tumorigenicity in lung cancer." (PMID 40599863, 2025). "It was found that ZNF322A, previously identified as an oncoprotein, could promote tumor cell growth and metastasis in lung cancer via ADD1 and CCND1; knockdown of ADD1 would suppress lung cancer cell migration and invasion." (PMID 29862265, 2018).
memory impairment (5 papers, 2021 to 2022). "Artificial inhibition of miR-135a-5p results in synaptic disorder and memory impairments via activation of the Rho-associated coiled-coil containing protein kinase 2 (Rock2)/Adducin 1 (Add1) signaling pathway." (PMID 33771994, 2021). "Loss of miR-135a-5p expression results in an increase in Rock2 activity and hyperphosphorylation of Add1 at Ser726, which in turn leads to dendritic abnormalities and memory impairments." (PMID 33771994, 2021).
colorectal cancer (4 papers, 2015 to 2022). A primary or metastatic malignant neoplasm that affects the colon or rectum. "To explore the role of ADD1-rs4963 in colorectal cancer (CRC), we conducted a case-control study with a total of 1054 CRC cases and 1128 matched controls in a Chinese population." (PMID 25816007, 2015). "Recently, a missense variant at the codon of ADD1's phosphorylation site, rs4963 (Ser586Cys), is reported to modify the risk of non-cardia gastric cancer and colorectal cancer (CRC)." (PMID 28476036, 2017). "Likewise, metastatic colorectal cancer cells SW620 showed higher expression of p35 and ADD1 than non-metastatic colorectal cancer cells SW480 did." (PMID 31548578, 2019).
Stroke (4 papers, 2009 to 2020). Sudden impairment of blood flow to a part of the brain due to occlusion or rupture of an artery to the brain. "ADD1, a gene associated with increased stroke risk, was reported to be in the vicinity of a lncRNA with increased expression in female IS patients compared to controls and was found in this study to be associated with DAS in male and female CE patients and male LVD patients." (PMID 33193047, 2020). "On the contrary, a population-based case control study on the same polymorphism found that diuretics protected ADD1 460 Trp carriers from combined nonfatal MI/nonfatal stroke outcome." (PMID 22135769, 2011). "At gene level, few were differentially expressed: ALDH2, ALOX5AP, F13A1, and IMPA2 (males, all stroke); ITGB3 (females, cardioembolic); ADD1 (males, atherosclerotic); F13A1, IMPA2 (males, lacunar); and WNK1 (females, lacunar)." (PMID 33193047, 2020).